SPRY4 (sprouty RTK signaling antagonist 4)
Diseases named in the same sentence as SPRY4 in open-access papers (continued):
Sharing a sentence is not in itself a finding about the gene and the disease.
lung carcinoma (11 papers, 2017 to 2025). "In the current study, we demonstrate that the loss of Spry4 in lung cancers is due to increased Spry4 mRNA degradation as a result of up-regulated KSRP expression." (PMID 28275056, 2017). "Lung carcinoma is a tumour entity where Spry4 is shown to interfere with the malignant phenotype of the cells." (PMID 40806483, 2025). "The antiproliferative capacities of the Kallmann-associated Spry4 mutant exceed those of the corresponding wt, when expressed in DMS114, a lung cancer-derived cell line where FGFR1 amplification was identified as a driver mutation." (PMID 40806483, 2025). "Like it is reported for lung cancer-derived cells, Spry4 expression interfered with cell accumulation upon time if compared with control-treated cells." (PMID 40806483, 2025). "2mRNA and protein stability: In non-small cell lung cancer, significantly upregulated KSRP protein promotes rapid decay of SPRY4 mRNA, leading to increased cell proliferation, migration, and invasion, thereby promoting lung cancer development." (PMID 38686189, 2024). "In 2006, they further discovered that the expression of Spry4 mRNA and protein was decreased in non‐small cell lung cancer (NSCLC) cell lines and poorly developed lung cell lines compared to untransformed human lung epithelial cell lines." (PMID 38686189, 2024). "Nonetheless, in lung cancer-derived cells Spry4 is reported to interfere with proliferation as well as migration via the Wnt-pathway." (PMID 33670044, 2021). "In AXL-high-expressing EGFR-mutated lung cancer cells, osimertinib exposure inhibits ERK phosphorylation and thereby decreases the expression of SPRY4 maintained by ERK-mediated MAPK signal." (PMID 32929081, 2020). "A concordant inhibition of proliferation and migration in case of Spry4 expression is reported for breast and lung cancer cells." (PMID 31374860, 2019). "On the contrary, up-regulation of KSRP in NSCLC leads to the destabilization of Spry4 transcripts, resulting in increased cell proliferation, cell migration, and invasion, which contribute to the development of lung cancer." (PMID 28275056, 2017). "Collectively, these results suggest that miR-411-5p/3p are required for NSCLC development by suppressing SPRY4 and TXNIP; thus, the miR-411-SPRY4-AKT axis might act as a promising target for lung cancer therapy clinically." (PMID 30390072, 2019). "This is the first report that SPRY4 might be a potential negative regulator of AXL signaling in lung cancer with driver oncogenes that is treated with osimertinib." (PMID 30651547, 2019). "However, the role of SPRY4 in prostate cancer and lung cancer is completely different." (PMID 38686189, 2024). "The MEK inhibitor trametinib inhibits the expression of SPRY4 in stromal-like KRAS mutant NSCLC, leading to the activation of AKT and ERK signals in stromal-like KRAS mutant lung cancer cells." (PMID 38686189, 2024). "Research has demonstrated that the oncogenic microRNA-141 directly targets tumor suppressor genes such as SPRY4 and TXNIP, leading to their downregulation and promoting the progression of lung cancer." (PMID 38686189, 2024). "This microRNA is capable of promoting lung cancer by subexpressing several regulators (SPRED1, SPRED2, SPRY1, RASA1, SPRY3 and SPRY4) in RAS / MAPK signaling, which leads to an increase in the signaling of this pathway." (PMID 29053755, 2017). "Further results indicated that, SPRY4 was downregulated in human NSCLC cell lines as well as in lung cancer samples compared with the non-tumor tissues." (PMID 30390072, 2019). "SPRY4 inhibited EGFR expression in NSCLC, a critical factor in lung cancer-targeted therapy." (PMID 30390072, 2019).
lung carcinoma (continued). "Interestingly, SPRY4 itself has also been shown to repress EMT in NSCLC and thus the SPRY4 locus, including both SPRY4 and SPRY4-IT1, appears to be highly important to the regulation of EMT in lung cancer cells." (PMID 28430163, 2017).
prostate carcinoma (11 papers, 2011 to 2024). A carcinoma that arises from epithelial cells of the prostate gland. "High methylation in the SPRY4 promoter region has been observed in patients with prostate cancer, colorectal cancer, and familial testicular cancer, leading to transcriptional inactivation of SPRY4 and promoting tumor occurrence and development." (PMID 38686189, 2024). "For example, SPRY4 has been shown to inhibit integrin-mediated cell spreading by interacting with testicular protein kinase 1 in prostate cancer cell lines." (PMID 26392417, 2015). "We were able to verify, in the majority of our samples (88 and 74%), a diminished expression of GADD45 and SPRY4 that were known to be inactivated by hypermethylation in prostate cancer." (PMID 26317032, 2014). "Their epigenetic analysis revealed methylation of a CpG island in the 5′-regulatory region of Spry4 in more than a half of all prostate cancer DNA samples studied which was significantly correlated with decreased expression of Spry4 mRNA." (PMID 24744103, 2014). "Both SPRY4 and SPRY4-IT1 have been observed to alter cell growth, migration and invasion in prostate cancer and melanoma." (PMID 29410498, 2018). "A recent report has shown that ETS1 knockdown in DU145 prostate cancer cells activates dual specificity phosphatase 4 (DUSP4), DUSP6, and sprouty RTK-signaling antagonist 4 (SPRY4)." (PMID 28474232, 2017). "Methylation of Sprouty-4 (SPRY4), an inhibitor of the receptor-transduced mitogen-activated protein kinase (MAPK) signalling pathway, has been detected in prostate cancer." (PMID 24521303, 2013).
glioma (8 papers, 2018 to 2025). A benign or malignant brain and spinal cord tumor that arises from glial cells (astrocytes, oligodendrocytes, ependymal cells). "Progression-free survival of GB patients and overall survival of adult glioma patients with high SPRY4 levels were reduced in our R2 genomics analysis, whereas other studies revealed that high expression of SPRY4 is associated with better prognosis for GB patients." (PMID 41516252, 2025). "SPRY4 has been identified as a biomarker gene by single-cell sequencing with differential expression in the different subtypes of glioma." (PMID 41516252, 2025). "Another study has shown down-regulation of SPRY4 as one of validated targets of miR-1908 in glioma samples." (PMID 36100870, 2022). "Another study in glioma has shown that miR-1908 has a role in enhancement of proliferation and invasion, as well as suppression of apoptosis through regulation of SPRY4/RAF1 axis." (PMID 36100870, 2022). "In accordance with our observation, an earlier report describes that Spry4 is often missing or deleted in gliomas." (PMID 31374860, 2019). "Furthermore, we found three EGFR and FGFR signaling feedback regulators common to all analyzed gliomas—SPRY4, ERRFI1, and RAB31—which can be used for creating new therapeutic strategies of suppressing the invasion and progression of gliomas." (PMID 36231068, 2022). "Furthermore, overall survival of adult glioma patients with high SPRY4 levels is strongly reduced, whereas in pediatric glioma patients, high expression of SPRY4 is associated with a non-significantly better prognosis." (PMID 41516252, 2025). "However, a recent study confirmed that, in gliomas, the expression pattern of SPRY4 may be related to the cell proliferation, metastasis, and epithelial–mesenchymal transition processes." (PMID 30322114, 2018). "In general, the activation of SPRY4, ERRFI1, and RAB31 can be used for developing new approaches to glioma therapy." (PMID 36231068, 2022). "We also detected that the upregulation of SPRY4, ERRFI1 and RAB31 provides a condition for feedback regulations of FGF and EGF signaling as well as can be applied in glioma therapy." (PMID 36231068, 2022). "The following two optimal genes, SPRY4 (rank 8) and BCL11A (rank 9), act differentially on the three glioma subtypes according to recent publications." (PMID 30322114, 2018). "The identification of the SPRY4, ERRFI1, and RAB31 as genes whose natural activation provides the inverse regulation of the processes of neurosphere formation can be used for creating new strategies of suppressing the invasion and progression of gliomas." (PMID 36231068, 2022). "Interestingly, we found three commonalities for all analyzed glioma feedback regulators of the EGFR and FGFR signaling pathways: SPRY4, ERRFI1 and RAB31." (PMID 36231068, 2022).
glioblastoma (6 papers, 2018 to 2025). The most malignant astrocytic tumor (WHO grade IV). "In glioblastoma, Spry3 and Spry2 have a tumour-promoting potential, while Spry4 was shown to interfere with malignant features of glioblastoma." (PMID 40806483, 2025). "In glioblastoma, for example, reduced signaling resulting in diminished pERK phosphorylation was observed as a result of Spry4 expression, but Spry3 exerted tumor-promoting activities without influencing these pathways." (PMID 34769378, 2021). "Spry3 potentiates the tumorigenic potential of glioblastoma cells and Spry4 functions as tumor-suppressing protein in this entity." (PMID 31374860, 2019). "In the presented study, we investigated the expression of Spry3 and Spry4 in brain cancer-derived cells and analyzed how a modulation of their expression influences the behavior of glioblastoma-derived cell lines." (PMID 31374860, 2019). "In our study, TQ treatment of A172 glioblastoma cells with 25 and 50 μM concentrations for 48 hours significantly up-regulated two candidate tumor suppressor genes: Sprouty RTJ Signaling Antagonist 4 (SPRY4) and Brain Expressed X-Linked 2 (BEX2)." (PMID 39874307, 2025). "While Spry4 expression was mitogen-dependent and repressed in a number of cells from higher malignant brain cancers, Spry3 levels neither fluctuated in response to serum withdrawal nor were repressed in glioblastoma (GBM)-derived cell lines." (PMID 31374860, 2019). "No direct evidence confirmed that SPRY4 may act differentially in glioblastoma and the two astrocytomas." (PMID 30322114, 2018).
colorectal cancer (5 papers, 2020 to 2025). A primary or metastatic malignant neoplasm that affects the colon or rectum. "This study aims to assess the role of SPRY4 in colorectal cancer (CRC) and uncover its underlying mechanisms." (PMID 33879635, 2021). "Despite being tumor suppressors in many types of cancer, SPRY1 is an oncogene in rhabdomyosarcoma, SPRY2 in colorectal cancer, and SPRY4 in gastric cancer." (PMID 41516252, 2025). "These research findings suggest that SPRY4, as a tumor suppressor in colorectal cancer, may have a complex role and be regulated by multiple factors, including gene expression regulation and epigenetic modifications." (PMID 38686189, 2024). "For the first time, we report that SPRY4 is epigenetically upregulated in colorectal cancer (CRC)." (PMID 36384366, 2023). "Furthermore, low expression of SPRY4 predicted poor prognosis in colorectal cancer." (PMID 38686189, 2024). "In human colorectal cancer tumors, overexpression of UHRF1 upregulates SPRY4 transcriptional activity by regulating 5-hydroxymethylcytosine levels in the SPRY4 locus, promoting tumor development." (PMID 38686189, 2024). "In addition, clinical data have correlated low expression of SPRY4 with a poor prognosis in PHCC, adult myeloid leukaemia, and colorectal cancer (CRC)." (PMID 36384366, 2023).
non-small cell lung carcinoma (5 papers, 2016 to 2024). A group of at least three distinct histological types of lung cancer, including non-small cell squamous cell carcinoma, adenocarcinoma, and large cell carcinoma. "Post-transcriptional degradation of SPRY4 transcripts has also been documented as a mechanism contributing to the tumor phenotype observed in non-small-cell lung cancer." (PMID 36384366, 2023). "For instance, miR-411-5p accelerates non-small cell lung cancer development by suppressing SPRY4 and TXNIP." (PMID 34903711, 2021). "In non-small cell lung cancer, peroxisome proliferator-activated receptor γ (PPARγ), a downstream target of Wnt7A/Fzd9 signaling, inhibits non-small cell lung cancer cell proliferation by up-regulating SPRY4 expression levels through regulating SPRY4 promoter activity." (PMID 38686189, 2024). "Additionally, SPRY4 inhibits tumor development by regulating cell differentiation in rhabdomyosarcoma and non-small cell lung cancer." (PMID 38686189, 2024). "Moreover, the tumor-suppressing function of SPRY4 that is triggered by upstream peroxisome proliferator-activated receptor gamma signalling is lost in non-small-cell lung cancer." (PMID 36384366, 2023). "In addition, epigenetic silencing of the lncRNA SPRY4 occurs in non-small cell lung cancer cells through direct transcriptional repression mediated by EZH2." (PMID 26848980, 2016).
osteosarcoma (5 papers, 2019 to 2025). A usually aggressive malignant bone-forming mesenchymal neoplasm, predominantly affecting adolescents and young adults. "Next, we wanted to investigate the function of the Spry4 mutation associated with Kallmann syndrome in osteosarcoma-derived cells where the wildtype Spry4 protein is unable to interfere with cell migration." (PMID 33670044, 2021). "Mutations in the SPRY4 protein inhibit cell migration in osteosarcoma-derived cell lines." (PMID 38686189, 2024). "Additionally, migration of normal embryonic lung fibroblasts and osteosarcoma-derived cells is potently inhibited by the tyrosine Spry4 variant, while an effect of the wildtype Spry4 protein is hardly measureable." (PMID 33670044, 2021). "Using the osteosarcoma-derived cell line U2OS, the effect of the two Spry4 variants on cell migration and cell proliferation was tested and compared to a control-treated cell population." (PMID 40806483, 2025). "The influence of Spry2 and Spry4 on the malignant phenotype of osteosarcoma is already investigated." (PMID 34769378, 2021). "Although in osteosarcoma-derived cell lines Spry2 protein shows excellent tumour-suppressing properties, Spry4 neither interferes with cell proliferation nor migration in the same experimental setting." (PMID 40806483, 2025). "While in our studies Spry4 wildtype protein failed to influence the activity of MAPK in WI-38 cells as well as in osteosarcoma-derived cells in response to FGF2 induction, the conversion of the serine at position 241 empowered the protein to interfere with FGF-mediated signal transduction." (PMID 33670044, 2021).
rhabdomyosarcoma (5 papers, 2015 to 2025). A rare aggressive malignant mesenchymal neoplasm arising from skeletal muscle. "Moreover, miR-411-5p is negatively regulated by transforming growth factor-β1 and acts as a tumor suppressor via directly downregulating SPRY4 in rhabdomyosarcoma." (PMID 34903711, 2021).
testicular germ cell tumor (5 papers, 2013 to 2023). A germ cell tumor arising from the testis. "Recent advances have implicated the KITLG/SPRY4/BAK1 and TGFβ/BMP-signaling (BMPR1B) pathways in germ cell tumor development, which include the control of differentiation, cell proliferation and apoptosis." (PMID 23599692, 2013). "The expression of SPRY4 was upregulated in testicular germ cell tumors." (PMID 31565549, 2019).
Anosmia (4 papers, 2018 to 2025). An inability to perceive odors. "The incidence of FGFR1 mutations in Kallmann syndrome is about 10%, and in the last decades many pathogenic mutations in associated genes including Spry4 have been identified in patients." (PMID 40806483, 2025). "In this manuscript, we aimed to investigate the effects of the Kallmann syndrome-associated Spry4 mutation c530A>G, which creates a lysine to arginine conversion at position 177 of the Spry4 protein." (PMID 40806483, 2025). "Further reports verified the contribution of Spry4 mutations in oligogenic variants of Kallmann syndrome." (PMID 40806483, 2025). "In summary, these data emphasize that like the other mutations associated with Kallmann syndrome the described Spry4 mutation creates a hyperactive version of a selective inhibitory molecule and can thereby contribute to a weakened FGF signaling." (PMID 33670044, 2021). "In order to investigate the role of the Spry4 mutation associated with Kallmann syndrome, we introduced a cytosine to adenine transversion on position 722 of the Spry4 coding sequence." (PMID 33670044, 2021). "Nonetheless, our data allow the conclusion that the substitution resulting from the Kallmann syndrome-associated Spry4 mutation creates a hyperactive form of Spry4." (PMID 33670044, 2021). "Summarized, these experiments demonstrated that in normal fibroblasts the investigated mutation found in Kallmann syndrome creates an altered Spry4 protein that is superior to the wt version in terms of its ability to inhibit ERK activation and the connected processes’ proliferation and migration." (PMID 40806483, 2025). "In our first series of experiments, we therefore wanted to test whether and to what extent a Spry4 protein, which is altered due to a mutation frequently associated with the diagnosis of Kallmann syndrome, influences proliferation and migration of human fibroblasts." (PMID 40806483, 2025). "In contrast, cell proliferation of DMS114 cells was slowed down efficiently by both versions of Spry4, but the protein adaptation created based on the alteration found in Kallmann-syndrome patients inhibited the process to a greater extent." (PMID 40806483, 2025). "SPRY4 variants have been found in a cohort of patients presenting with hypogonadotropic hypogonadism with or without anosmia (HH17, OMIM #615266)." (PMID 29378665, 2018).
gastric cancer (4 papers, 2017 to 2025). A primary or metastatic malignant neoplasm involving the stomach. "High expression of SPRY4 is associated with several clinical pathological features of gastric cancer, including depth of infiltration, TNM staging, lymph node metastasis, and regional lymph node metastasis." (PMID 38686189, 2024). "In in vitro experiments, knockdown of SPRY4 expression in gastric cancer cell lines inhibited cell proliferation and migration." (PMID 38686189, 2024). "Furthermore, the mRNA level of SPRY4 was validated in 78 cases of human gastric cancer tissues and non-gastric cancer tissues using RT-qPCR, confirming the high expression of SPRY4." (PMID 38686189, 2024). "In 2020, Chinese researchers analyzed the expression levels of SPRY4 in gastric cancer (GC) tissues from the TCGA database and found that SPRY4 was upregulated in human gastric cancer tissues, indicating that its expression levels were higher than in normal gastric tissues." (PMID 38686189, 2024). "In gastric cancer, LINC00675 suppresses cell proliferation and migration via downregulating the H3K4me2 level at the SPRY4 promoter." (PMID 34335862, 2021).